CRP (C-reactive protein)
Diseases named in the same sentence as CRP in open-access papers (continued):
Sharing a sentence is not in itself a finding about the gene and the disease.
diabetes (continued). "Blood chemistry tests showed diabetes patients had elevated whole blood leukocyte counts (median 16.3 × 109/L [interquartile range (IQR) 11.6–22.6 × 109/L]) and C-reactive protein was elevated (>8.0 mmol/L) in 169 of 173 episodes (98%; median 172 mg/L [IQR 71–298 mg/L])." (PMID 27845429, 2016). "C-reactive protein (CRP) is a well-established biochemical marker of inflammation and has been used to predict future cardiovascular disease, metabolic syndrome, and future development of type 2 diabetes mellitus." (PMID 26884762, 2016). "However, the association weakened below significance (P = 0.073) after controlling for possible confounders (age, sex, hypertension, diabetes mellitus, atrial fibrillation, hyperlipidemia, CCI, NIHSS, CRP, albumin, and eGFR)." (PMID 27096104, 2016). "As the results showed that people with hypertension, diabetes or had higher hs-CRP concentrations; if coexisting with hypertension, diabetes, high cholesterol, and obesity, 63.0% of them were in the top quartile of hs-CRP." (PMID 27589783, 2016). "Plotting the empirical density of log(CRP) for adults who are normal (do not have prediabetes or diabetes), adults who have prediabetes, and adults who have diabetes clearly reveals differences in distribution and hence percentiles." (PMID 27034909, 2016). "For both males and females, it is not a simple shift in location of CRP between normal and diabetes groups; there appears to be increasing differences as the percentile increases." (PMID 27034909, 2016). "Neither diabetes nor smoking influenced the effectiveness of aspirin and inflammatory condition shown by elevated CRP also failed to influence COX1 acetylation." (PMID 26980433, 2016). "Adherence to the ‘high-sugar’ dietwas also significantly associated with age and intake of total energy and inverselyassociated with prevalent diabetes, glucose, HDL and CRP, but not significantly associatedwith SBP or vWF." (PMID 27620002, 2016). "In animal models of diabetes, histidine supplementation could reduce the levels of IL-6, TNF-α and CRP." (PMID 27409634, 2016). "In females, SUA was independently associated with LVMI (β = 0.375, p = 0.002), after adjustment for age, menopause, BMI, hypertension, diabetes mellitus, dyslipidemia, smoking, eGFR, usage of ACEI/ARB, usage of diuretics, hs-CRP, duration of obstructive HCM, and resting LVOT gradient." (PMID 27054027, 2016). "In chronic settings, such as in patients with diabetes, some authors found a positive correlation between CRP and blood AGEs, while others did not." (PMID 27529340, 2016). "In the presence of falciparum malaria, respondents with diabetes maintained their superiority (P < 0.05) over their nondiabetic counterpart in terms of levels of CRP, peroxides, BMI, WHR, and WC but comparable (P > 0.05) TAP and BAI levels." (PMID 27298824, 2016). "Serum magnesium levels are also negatively correlated with levels of CRP and IL-6 in patients with and without diabetes." (PMID 27547762, 2016). "In the females, respondents with diabetes exhibited higher (P < 0.05) BMI, WC, CRP, and peroxides than their nondiabetic controls." (PMID 27298824, 2016). "Among the 3 groups, the diabetes with or without obesity groups had increased levels of CRP, IL-6, IL-17, and A-FABP compared to the simple obesity group (P < 0.05)." (PMID 27819006, 2016). "A funduscopic examination should be performed as soon as possible after the onset of symptoms in those with elevated CRP, high WBC, unknown origin of fever, and/or a history of diabetic mellitus." (PMID 25802752, 2015). ": To evaluate the correlation between preoperative C-reactive protein andpostoperative complications risk in obese patients (grades II and III) afterRoux-en-Y gastric bypass, with and without type 2 diabetes mellitus." (PMID 26537265, 2015). "In the subgroups of patients with diabetes or increased C-reactive protein an elevated UA also did not alter the incidence of events or death (data not shown)." (PMID 25685556, 2015).
diabetes (continued). "Elevated levels of CRP are described in persons with type 2 diabetes; however, it is not clear if they are related to the presence of obesity, diabetes, or both." (PMID 25648962, 2015). "Patients with diabetes and periodontal disease had significantly higher mean levels of serum TNF-α (1.79 ± 0.19 vs 0.82 ± 0.17 pg/mL), IL-6 (0.57 ± 0.07 vs 0.38 ± 0.05 pg/mL), and CRP (0.39 ± 0.11 vs 0.21 ± 0.08 mg/L) by comparison with healthy subjects." (PMID 26644840, 2015). "The CRP-mediated link between depression/anxiety and the development of LUTS was not significant after adjustment for other known confounders of LUTS (e.g. hypertension, diabetes, obesity, OSA, widowhood, elevated LDL cholesterol, lower physical activity)." (PMID 26445118, 2015). "In contrast, neither the indirect effects of smoking on diabetes through leptin nor CRP levels were significant, as the corresponding BC 95% CIs included zero." (PMID 25400076, 2015). "The association was nearly significant for low serum creatinine (P = 0.051) but not significant for gender, diabetes, CRP >5 mg/L and low protein intake." (PMID 26322258, 2015). "In our analysis, adiponectin concentration appeared to partially mediate the effect of smoking on diabetes, while leptin and CRP levels did not." (PMID 25400076, 2015). "Eleven patients reported a serious AE (SAE); the events were considered drug-related in three patients (grade 3 ALT/grade 2 AST increase/grade 2 C-reactive protein increase in one patient, grade 2 AST/ALT increase in one patient, and grade 3 diabetes mellitus in one patient)." (PMID 26410424, 2015). "Participants with diabetes also had higher blood pressures, triglycerides, and C-reactive protein (CRP) levels than those without diabetes." (PMID 26186342, 2015). "Compared with subjects with no change in CAC values, those with an increase in CAC levels were more likely to be older, male, obese, or heavy drinkers and have diabetes or hypertension; higher BMI, blood pressure, fasting glucose, LDL, ALT, GTP, or CRP; and lower HDL cholesterol." (PMID 26538347, 2015). "This association was attenuated and was no longer statistically significant when models were further adjusted for insulin, adiponectin, C-reactive protein, and estradiol and when additionally restricted to those without a history of diabetes." (PMID 26106415, 2015). "Among patients without diabetes mellitus who were not receiving statin therapy, approximately 30% had CRP levels ≥3 mg/L, and approximately 50% had CRP levels ≥2 mg/L, including those at intermediate levels of traditionally estimated cardiovascular risk." (PMID 24564178, 2014). "AST and CRP were slightly higher in those of both sexes with diabetes; however, the difference was not significant in either sex." (PMID 24502834, 2014). "In our study, HIF-1α correlated with some cardiovascular risk factors (CRP, IL-6, UKPDS, HbA1c and FBG), but were not correlated with others (diabetes duration, age and LDL)." (PMID 24564828, 2014). "SFT showed positive correlations with BMI (r = 0.54), hs-CRP (r = 0.24), and TC (r = 0.20) and negative correlations with duration of diabetes (r = -0.25) in women (data not shown)." (PMID 24678948, 2014). "Detectable levels of anti-EPC antibodies, that correlated with age, Framingham risk score and CRP concentrations but did not associate with levels of LDL, HDL, hypertension or diabetes, were detected." (PMID 24945945, 2014). "HIF-1α levels positively correlated with CRP, IL-6, UKPDS risk score, HbA1c, FBG, and CACS, but did not correlate with diabetes duration, age, and LDL." (PMID 24564828, 2014). "Forty-six (70% females) obese subjects (BMI≧30 kg/m2) without known diabetes and without inflammatory disease (CRP<10 mg/l) were included." (PMID 25437865, 2014). "Further adjustment for hypertension, diabetes, CRP, HOMA-IR or LDL-cholesterol did not materially alter the estimates (data not shown)." (PMID 24586219, 2014).
diabetes (continued). "There were significant differences in the ages, daily cigarette consumptions, family histories of diabetes, and serum CRP levels of the current smokers with and without type 2 diabetes." (PMID 25105149, 2014). "Multivariable Cox regression analysis showed that PEDF independently predicted CKD progression (adjusted HR = 3.77; 95% CI = 1.79–7.95; P < .001) in a model that included sex, age, WC, diabetes duration, HbA1c, SBP, antihypertensive treatment, CRP, and eGFR using CKD-EPI (eGFR-EPI)." (PMID 25166721, 2014). "In particular, 34.0 to 38.2% of patients without diabetes mellitus who were not receiving statin therapy, and at an estimated intermediate 10-year cardiovascular risk according to SCORE or FRS, had CRP levels ≥3 mg/L, and 49.2 to 54.1% had CRP levels ≥2 mg/L." (PMID 24564178, 2014). "In T2D, in a study of 18 patients who had been hospitalized to initiate insulin therapy because of poor diabetes control, CRP values, but not MCP1 and fibrinogen levels, were decreased 2 weeks after initiation of insulin therapy." (PMID 24495560, 2014). "Our study found that individuals with diabetes and depression had significantly higher 24-h urine free cortisol levels and CRP than individuals without depression." (PMID 23410093, 2013). "In addition, age, diabetes, preexisting CAD, serum albumin, ferritin, CRP, residual GFR, peritoneal Kt/V urea, nPCR, and %LBM were revealed as predictors of mortality." (PMID 24349396, 2013). "In our study, diabetes mellitus and high hs-CRP levels had a negative effect on the development of CAS." (PMID 24204905, 2013). "Among patients without obstructive CAD, diabetes mellitus contributes to CAS development in men with low hs-CRP levels, but not in women." (PMID 24204905, 2013). "The significant correlates were systolic blood pressure (SBP), C-reactive protein (CRP), uric acid, diabetes, gamma-glutamyl transferase (GGT) (marginally significant, p = 0.054) and serum albumin (negative association) for ACR 17+ (mg/g) for men and 25+ for women." (PMID 23947772, 2013). "Effect of STZ- induced (50 mg.kg−1, 8 weeks) diabetes and daily oral administration of quercetin (50 mg.kg−1) on body weight, blood glucose, serum insulin, insulin resistance (IR) index, TNF-α, C-reactive protein (CRP), systolic BP." (PMID 23717483, 2013). "Independent correlates were SBP, uric acid, diabetes, total cholesterol, alanine amino transferase (ALT), Cystatin C and serum albumin (negative association) for overt albuminuria; and SBP, CRP and serum albumin only for microalbuminuria." (PMID 23947772, 2013). "Several studies report an association between single-nucleotide polymorphisms (SNPs) in the CRP gene with variation in blood levels of CRP with cardiovascular disease (CVD) and other diseases such as diabetes, microangiopathic stroke, insulin resistance, metabolic syndrome, and hypertension." (PMID 23049543, 2012). "First, univariate logistic regression was used for the six miRNAs along with sepsis stage (sepsis = 1, severe sepsis = 2, septic shock = 3), age, sex, SOFA scores, APACHE II scores, CRP and PCT levels, white blood cell counts (WBC), coronary heart diseases (CHD), diabetes, hypotension, and COPD." (PMID 22719975, 2012). "Out of the model’s explanatory variables, ‘CRP’ (Beta = −.279, p = .000) and ‘CVD’ (Beta = −.233, p = 002) showed the highest levels of explanation, followed by ‘GFR’ (Beta = .191, p = .003), ‘diabetes’ (Beta = −.160, p = .008) and ‘age’ (Beta = −.158, p = 021)." (PMID 22710013, 2012). "The association between serum total testosterone levels and NAFLD was examined by employing multiple logistic regression analysis with potential confounding variables such as age, smoking, diabetes, exercise, BMI, TGs, HDL-C, HOMA-IR, hs-CRP, and VAT controlled." (PMID 22691278, 2012).
diabetes (continued). "We concluded that pulse pressure, HDL-cholesterol, and high-sensitive CRP are variables correlated with carotid IMT in treated hypertensive women with no diabetes or previous cardiovascular events." (PMID 22701780, 2012). "The main result of this work is that CRP was not independently associated with diabetes when we take into account the VO2 level and that the VO2 level had a strong association with CRP independently of diabetes." (PMID 22566996, 2012). "The effects of fisetin on both plasma levels of CRP and kidney expression of OPN as well as albuminuria suggest that it has both systemic and tissue-specific effects on inflammation that can reduce the consequences of diabetes." (PMID 21738623, 2011). "His laboratory blood values showed a non-regulated diabetes mellitus with hyperglycemia of 32 mmol/L, white blood cell count of 18 × 109/L with 81.6% polymorphonuclear cells (PMNs), elevated C-reactive protein (CRP), hemoglobin, sodium and creatinine." (PMID 22196774, 2011). "Furthermore, our data revealed for CLR elevated C-reactive protein values and a high PREDICT-score (including an age >65 years, acute coronary syndrome, diabetes mellitus, renal failure, and reduced left ventricular function) as risk factors." (PMID 21226927, 2011). "MLR analysis showed that diabetes status did not affect the relationship between WC and BMI with ln hs-CRP in females." (PMID 20617007, 2010). "When controlling for age, smoking, and medications, males without diabetes exhibited a stronger and significant relationship between WC and ln hs-CRP compared with males with diabetes (B = 0.048, P < 0.001 and B = 0.004, P = 0.712, respectively)." (PMID 20617007, 2010). "Relationship between high-sensitivity C-reactive protein (hs-CRP) and adiposity by diabetes status and gender in Cuban-Americans with and without type 2 diabetes (T2D) was studied." (PMID 20617007, 2010). "In crude models, CRP was also significant for the full population and for individuals without diabetes." (PMID 20123638, 2010). "In general, body fatness had a greater affect on hs-CRP for subjects without diabetes than subjects with diabetes, which was an unexpected result." (PMID 20617007, 2010). "The OR for newly diagnosed diabetes by the glucose criterion were significantly higher for GGT but not for CRP in men and women, which was, however, not observed for newly diagnosed diabetes by the HbA1c criterion." (PMID 21076541, 2010). "In comparison with subjects without diabetes by HbA1c criterion, those with newly diagnosed diabetes by HbA1c criterion had higher serum FPG, 2hPG, HDL, TC, and fasting insulin levels in men and higher WC, serum FPG, 2hPG, CRP, and fasting insulin levels in women." (PMID 21076541, 2010). "The highest percent difference in CRP [71.3% (95% CI, 18.4–147)] was observed for individuals without diabetes residing within the highest versus lowest level of VMT/mi2." (PMID 20123638, 2010). "The slope for the relationship between BMI and ln hs-CRP was stronger for persons without diabetes than with diabetes (B = 0.099 and B = 0.055, respectively), but both slopes were significantly different than zero (P < 0.001)." (PMID 20617007, 2010). "Thirty-four children (25 males; median age 10.8 ± 3.4 yrs) with severe obesity (BMI >95%) were screened for diabetes with oral glucose tolerance test (OGTT), systemic inflammation with C-reactive protein (CRP) and gut inflammation with rectal nitric oxide (NO) and faecal calprotectin." (PMID 20920305, 2010). "It is also well known that CRP concentration was elevated in severely obese patients but this elevation was moderate and not related to metabolic syndrome, diabetes, and more importantly to steatohepatitis." (PMID 19222849, 2009). "After adjustment for CRP and insulin, ALT and GGT were still predictive of incident diabetes." (PMID 18533046, 2008).
diabetes (continued). "The findings were also replicated in a subcohort including only individuals with no CHD or diabetes (n = 2608 for CRP measured at mean age 61, n = 2393 for CRP at mean age 49)." (PMID 18714381, 2008). "Maternal features of MetSyn were defined by the presence of pre-pregnancy diabetes mellitus, body weight ≥ 90th centile among controls, non-white ethnicity and/or serum highly sensitive C-reactive protein (hsCRP) ≥ 75th centile of controls." (PMID 17880716, 2007). "All participants underwent assessment of serum C-reactive protein (CRP), uric acid, and postprandial blood sugar (PPBS) levels, along with clinical evaluation of body mass index (BMI), history of polycystic ovary syndrome (PCOS), and family history of diabetes mellitus." (PMID 41200603, 2025). "As negative controls, we used C-reactive protein →Type-2-diabetes 19 instrumented from IL6R48, LDL-C→BMI instrumented from PCSK949 and C-reactive protein →coronary artery disease instrumented from CRP50, based on established and disproven causality from these loci." (PMID 40610416, 2025). "Moreover, they showed higher values of glycemic (FPG and HbA1c) and inflammatory (CRP, TNF-alpha, and ESR) markers, as well as a lower GFR, lower levels of HDL cholesterol, and a higher prevalence of hypertension, diabetes mellitus, ischemic heart disease, peripheral artery disease, and cancer." (PMID 41106480, 2025). "However, diabetes, hypertension, and the chronic inflammation biomarker CRP did not demonstrate a significant mediating effect." (PMID 40405968, 2025). "Adjusted models showed that CAUTI, delayed active therapy, higher baseline CRP, and diabetes increased the odds of non-response, whereas early catheter removal (adjusted odds ratio [aOR] 0.5, 95% confidence interval [CI] 0.3–0.9) and early IV-to-oral switch (aOR 0.4, 0.2–0.8) were protective." (PMID 41462885, 2025). "Beyond its local periodontal effects, SDD may also reduce systemic inflammatory mediators such as C-reactive protein (CRP), interleukin-6 (IL-6), and tumor necrosis factor-alpha (TNF-α), particularly in systemically vulnerable populations like individuals with diabetes or cardiovascular disease." (PMID 41465800, 2025). "Furthermore, data about metabolic-related diseases such as diabetes, obesity, and levels of inflammatory markers such as C-reactive protein were not available." (PMID 41226724, 2025). "Notably, patients with diabetes for ≥10 years were generally older and were more likely to have CKD, a lower left ventricular ejection fraction, and lower HDL-cholesterol levels, as well as higher levels of C-reactive protein, fasting glucose, and HbA1c." (PMID 40283627, 2025). "Third, elevated CRP levels may reflect higher disease activity in arthritis patients, which could worsen joint damage and contribute to the development or progression of comorbid conditions such as CVD and diabetes, ultimately affecting survival outcomes." (PMID 39980916, 2025). "Despite periodontitis having been consistently associated with a number of chronic conditions such as cardiovascular diseases, diabetes and metabolic syndrome, CRP, lipids and glycaemic levels are not routinely assessed in dental practice because of logistic and financial constraints." (PMID 40701837, 2025). "Pro-inflammatory conditions (diabetes, autoimmune disease) may elevate baseline CRP and modulate early postoperative kinetics; without these variables, we could not adjust for potential confounding." (PMID 41153812, 2025). "Model 2 adjusted for age, gender, race, hypertension, diabetes mellitus, smoke, drink, body mass index, left ventricular hypertrophy at ECG, antiarrhythmic medications, plasma creatinine, metabolic equivalent, LDL cholesterol, CRP, and angiotensin-converting enzyme inhibitors." (PMID 41373955, 2025).